RNY3P4 (RNY3 pseudogene 4)
Gene: Miscellaneous RNA gene on chromosome 13 (23,152,586 to 23,152,686, reverse strand). Ensembl gene ENSG00000207157.
Homologues: Orthologues: chimpanzee Y_RNA (99% identical), macaque Y_RNA (94% identical), pig Y_RNA (88% identical), dog Y_RNA (87% identical). Paralogues in human: Y_RNA (90% identical), Y_RNA (89% identical), RNY3 (88% identical), Y_RNA (88% identical), RNY3P1 (87% identical), Y_RNA (87% identical), Y_RNA (86% identical), Y_RNA (85% identical), RNY3P14 (84% identical), RNY3P16 (84% identical), RNY3P2 (84% identical), Y_RNA (84% identical), and 93 more.